IL1B (interleukin 1 beta)
Diseases named in the same sentence as IL1B in open-access papers (continued):
Sharing a sentence is not in itself a finding about the gene and the disease.
COVID-19 (continued). "Based on the reported increase in pyroptosis-related IL-1β, single inhibition of IL-1 pathway using recombinant IL-1RA anakinra was administered to critical COVID-19 patients without immunological stratification but proved unsuccessful." (PMID 37582864, 2023). "Interestingly, levels of IL-1β and CXCL8 in COVID-19 BAL fluid correlated positively with the elastinolytic and gelatinolytic activities measured." (PMID 34793331, 2022). "Cytokines, such as IL-1β, IL-6, IFN-γ-induced protein 10 (IP-10), TNF-α, IFN-γ, macrophage inflammatory protein-1α and-1β (MIP-1α and-1β), and vascular endothelial growth factor (VEGF) are raised in COVID-19 patients." (PMID 36439786, 2022). "Besides IL-1β, IL-6, and TNF, several cytokine storm-related factors are potential therapeutic targets for the treatment of severe COVID-19 patients." (PMID 34983527, 2022). "Since IL-1β can be released without pyroptosis, the two processes, cytokine release and cell death, need to be studied independently during COVID-19 pathogenesis." (PMID 35244141, 2022). "The IL-6, IL-1β, TNF-α, and IL-10 levels were consistently upregulated in patients with COVID-19." (PMID 36230930, 2022). "During SARS-CoV-2 infection, inhibition of Caspase-8 resulted in decreased IL-1β secretion, but not less viral replication, suggesting the involvement of Caspase-8 in pro-inflammatory signaling during COVID-19." (PMID 35244141, 2022). "A recent comprehensive meta-analysis reported the enhanced level of Interferon-γ (IFN-γ), TNF-α, IL-10, IL-8, IL-6, IL-4, IL-2R and IL-2, whereas no significant increase in IL-17 and IL-1β level among severe COVID-19 patients." (PMID 36298704, 2022). "The host immune response of COVID-19 presents a signature called “the global immune signature” of SARS-CoV-2 infection, which consists of elevated serum cytokines (particularly IL-1β, IL-6 and TNF-α), impaired IFN responses, and peripheral lymphopenia as markers of severe disease." (PMID 35982454, 2022). "High levels of IL-1β, IL-6, and TNF-α in hyperinflammatory conditions, which are strong inducers of hyaluronidase, lead to the production and accumulation of HA in the alveolar spaces in severe COVID-19 patients." (PMID 35741101, 2022). "Indeed, elevated levels of various interleukins such asIL-6, IL-1β, TNF-α, IL-10, and IL-8 and the chemokine MCP1 have been well documented in patients with severe COVID-19." (PMID 36016187, 2022). "We included in our tests a set of cytokines and chemokines with serum concentrations that were shown to increase during COVID-19, and this increase might also be reflected in breastmilk: TNF-α, IL-6, IFN-β, IL-1β, IFN-γ, IL-2, GM-CSF and IL-5, IP-10." (PMID 36560410, 2022). "Elevated levels of cytokines such as IL1B, IL7, IL8, IL9, and IL10, monocyte chemoattractant protein and tumor necrosis factor (TNF), among others, in COVID-19 have been reported and elevated proinflammatory cytokine levels have been found to correlate with disease severity." (PMID 35172279, 2022). "In this study concentrations of TNF-α, IL-1b, IL-2, IL-4, IL-5, IL-6, IL-8, IL-10, IL-12 p70, GM-CSF, and IFN-γ were determined by a magnetic bead assay in tear film collected from 232 symptomatic COVID-19 patients." (PMID 35508669, 2022). "In this study, we found that exosomes from COVID-19 patients stimulate NLRP3 inflammasome formation and IL-1β production in endothelial cells and may promote a systemic inflammatory response." (PMID 35587188, 2022). "TNF-, IL-2, IL-6, IL1B, IL7, IL10, IFN-, GCSF, CXCL10, CCL2, ferritin, D-dimer, fibrinogen, leukocytosis, and C-reactive protein (CRP) levels are significantly higher in critically ill COVID-19 patients." (PMID 35645351, 2022). "This post-COVID-19 inflammatory syndrome was originally diagnosed as Kawasaki disease; however, patients with MIS-C display more pronounced lymphopenia, thrombocytopenia, anemia, and elevated serum IFN-γ, IL-1β, IL-6, IL-10, and IL-17 levels." (PMID 35464491, 2022).
COVID-19 (continued). "First, the collective profile of cytokines produced matches three core cytokines of the COVID-19 cytokine storm, IL-1β, IL-6, and IL-8, with no anti-inflammatory cytokines produced." (PMID 36296272, 2022). "COVID-19 outcomes were found to be adverse for CCL3 and IL1B." (PMID 36225326, 2022). "As for the second signal, LNPs designed in a similar fashion as for the COVID-19 mRNA vaccines—but without mRNA—induced a strong pro-inflammatory cytokine profile (including IL-1β and IL-6) in mice upon injection into the skin." (PMID 35890284, 2022). "Finally, using a Bayesian Network model, we identified FOS, CXCL8, IL1β, CST3, PSAP, CD45 and CD74 as predictors of the COVID-19 disease." (PMID 36532041, 2022). "Severe COVID-19 disease is associated with a so-called “Cytokine Storm”, which is a dramatic increase in inflammatory cytokines/chemokines (especially IL-1β, IL-6, IL-8, and TNF-α) and other inflammatory factors that promote tissue injury and can predict the severity of COVID-19 and survival." (PMID 36296272, 2022). "Previous studies have shown that proinflammatory markers, including IL-6, IL-8, IL-1β, and TNFα, are significant predictors of COVID-19 disease severity, regardless of demographics or comorbidities." (PMID 36865568, 2022). "This has important implications for the hypothesis that the S1 spike protein may contribute to pathogenicity in both COVID-19 and PASC because IL-1β is a primary cytokine candidate to drive the COVID-19 cytokine storm and downstream cytokine production." (PMID 36296272, 2022). "In response to the SARS-CoV-2 S protein, NLRP3 expression and IL-1β release are upregulated in macrophages from patients with COVID-19 but not in macrophages from healthy patients." (PMID 36419185, 2022). "In a proteomic analysis by mass spectrometry, we did not detect NLRP3, caspase-1, IL-1β, or NF-κB proteins in the COVID-19 patient exosomes." (PMID 35587188, 2022). "RNA sequencing of the early recovery stage of COVID-19 showed that classical CD14++ and CD14++ IL-1β+;monocytes are of greater abundance with high expression of inflammatory genes, indicating that IL-1β may be a potential target for the COVID-19 intervention." (PMID 36090995, 2022). "Raised concentrations of IL-1β, IFN-γ, MCP1, and IP10 in ICU COVID-19 patients might stimulate the activation of T helper 1 cells to further increase inflammation." (PMID 35782361, 2022). "The SARS-CoV-2 spike protein triggers inflammasome activation and an IL-1β release in macrophages obtained from COVID-19 patients but not in macrophages from healthy SARS-CoV-2-naive controls." (PMID 35847031, 2022). "Furthermore, Ruxolitinib, a JAK1/JAK2 inhibitor acting downstream of JAK-dependent chemokines/cytokines such as IFN-γ, IL-1β, IL-6, TNF, G-CSF, CXCL9, and CXCL10, has shown promising results in treating COVID-19." (PMID 35269470, 2022). "PC2 separated COVID-19 patients from other forms of CAP due to elevated levels of IL-1α and IL-1β (PC2 scores for COVID-19 versus both other groups P<0·001, not significant between CAP-flu and CAP-strep)." (PMID 35660785, 2022). "By comparing healthy donors, patients with mild or severe COVID-19, and patients with severe influenza, they observed that all PBMC cell types of COVID-19 displayed hyper-inflammatory signatures, marked by a TNF/IL-1β-mediated inflammatory response, as compared to severe influenza." (PMID 35663932, 2022). "Exoproteome-targeting autoantibodies, which can perturb cell signaling and targeted killing of specific cell populations via Fc receptors and complement as well as suppress IL-1β, GM-CSF, and IL-21, are prominent in acute COVID-19 regardless of clinical stage." (PMID 35912863, 2022). "In SARS-CoV-2 infected lung, presence of IL-1β, TNFα, IL-6, and IL-8 indicate IL-17 induced MAPK and NF-κB mediate signaling; MAPK was shown to be activated during the acute phase of SARS-CoV-2 infection in nasopharyngeal swabs of severe COVID-19 patients." (PMID 36136963, 2022).
COVID-19 (continued). "Moreover, a positive correlation was seen between levels of IL-1β or IL-17A and CXCL8 in the BAL fluid of the patients with COVID-19." (PMID 34793331, 2022). "Immunohistochemical staining showed that endothelial cells expressed IL-1β in lung samples obtained from patients of COVID-19 but not in those obtained from control individuals (p < 0.001)." (PMID 34463916, 2022). "In addition, IL-1β, IL-4, IL-6, IL-18, IL-35, PGE2, and TXA2 levels in moderate and severe COVID-19 patients were significantly higher (p < 0.001) than in healthy controls." (PMID 36298501, 2022). "Orosomucoid is known to be regulated by TNF-β, IL1β, IL6 and IL6-related cytokines, along with immunomodulating effects like inhibiting neutrophil migration, and has been employed as a biomarker in COVID-19." (PMID 35438176, 2022). "Levels of IL-1β were not affected, while, in contrast, serum IL-18 was increased in fatal COVID-19 cases." (PMID 35386707, 2022). "Our data show that the levels of these IL-1α, IL-1β IL-6 and IL-18 cytokines are significantly lower in severe COVID-19 survivors than in non-survivors." (PMID 36142255, 2022). "Importantly, above immune findings were used for a Bayesian network model, which significantly revealed FOS, CXCL8, IL1β, CST3, PSAP, CD45 and CD74 as COVID-19 severity predictors." (PMID 36532041, 2022). "According to previous publications and despite the evidence of inflammasome activation during COVID-19, IL-1β has not been detected in the blood samples of COVID-19 patients." (PMID 35663992, 2022). "Given that plasma cytokine levels decrease after SARS-CoV-2 infection while IL-1β, IL-6, and TNF remain stable in individuals with ongoing PASC, we next asked whether there are patterns in active COVID-19 that provide a mechanistical link to this observation." (PMID 35732153, 2022). "Peripheral blood mononuclear cells (PBMCs) derived from severely ill COVID-19 patients display elevated expression of highly active NLRP3 inflammasome, as reflected by abundant levels of cleaved caspase-1 as well as mature IL-1β and IL-18 released upon stimulation in vitro." (PMID 36209522, 2022). "Our findings indicated elevated levels of IL-1β only systemically in COVID-19 patients and no significance was found either in airway or when groups with distinct outcomes were compared." (PMID 35720401, 2022). "In addition, high blood levels of IL-1β, IL-2, IL-8, IL-17, G-CSF, GMCSF, IP-10, MCP-1, and TNF-α are indicative for severe COVID-19." (PMID 35883640, 2022). "The cytokine storm has already been attenuated following recovery from COVID-19, as levels of TNF-α, free active TGF-β, IFN-γ, IL-1β, IL-2, IL-4, IL-6, IL-8, IL-10, IL-12p70, IL-17 and MCP-1/CCL2 during convalescence were not higher compared to healthy volunteers." (PMID 35757700, 2022). "Regarding the hyperinflammation, we observed BK1-8 was positively and significantly related to four out of five inflammation markers studied (CRP, ferritin, IL-1β, IL-6, and TNF-α), suggesting a potential role of this peptide in patients with COVID-19’ inflammation." (PMID 35812405, 2022). "The correlation analysis of specific serum biomarkers with 25OHD indicated that the vitamin D action in COVID-19 might involve regulation of INOS1, IL1B, IFNg, cathelicidin-LL37, and ICAM1." (PMID 34836309, 2021). "Elevated production of inflammatory mediators at day 7 postinfection, a late time point, indicates that a profound immune response resulted from infection and aligns with increased levels of inflammatory mediators, including IL-1β, IFN-γ, TNF-α, and CXCL10, detected in COVID-19 patients." (PMID 33879586, 2021). "IFN, TNF-α, and IL-1β co-drive inflammatory responses in the monocytes of patients with severe COVID-19, but not in those of patients with mild COVID-19." (PMID 34746034, 2021).
COVID-19 (continued). "The binding of COVID-19 to the Toll-like receptor (TLR) led to the release of pre-IL-1β, which was cleaved by caspase-1, followed by the activation of the inflammasome and the production of active mature IL-1β, which is a mediator of lung inflammation." (PMID 34164371, 2021). "In addition, from the analysis of cytokines in our patients we identified a subgroup, called COVID-plus, including COVID-19-positive patients who presented much higher levels of IL-6, TNF-α, IL-1β, and CD25 than other groups." (PMID 34578450, 2021). "In this study, we focused on TNFα, IL-1β, and IL-6 as known pro-inflammatory markers of acute inflammatory response, along with CXCL8/IL-8 because of its potent role in the recruitment and activation of neutrophils, commonly elevated in patients with COVID-19." (PMID 34360706, 2021). "High concentrations of IL-1β, IFN-γ, IP-10, and MCP-1 in COVID-19 patients have also been detected." (PMID 33746897, 2021). "Our results indicated that vitamin D treatment shortened the hospitalization period, decreased the mortality rate, and that the effect of vitamin D in COVID-19 might involve regulation of INOS1, IL1B, IFNg, cathelicidin-LL37, and ICAM1." (PMID 34836309, 2021). "The cytokine profile of patients with severe COVID-19 is characterized by an increase of several cytokines, mainly (but not restricted to) IL-1β, IL-2, IL-6, IL-7, IL-8, and TNF-α." (PMID 33669218, 2021). "Many inflammatory cytokines (Interferon-alpha (IFN-α), interleukin-1beta (IL-1β), interleukin 6 (IL6), interleukin 12 (IL-12), tumor necrosis factor-alpha (TNF-α), and transforming growth factor-beta (TGFβ) and chemokines were detected in COVID-19 patients." (PMID 34908920, 2021). "Notably, out of 27 differentially expressed proteins, 15 were found to be regulated by IL-1β, IL-6, or tumor necrosis factor (TNF), which are seen at markedly higher levels in most severe COVID-19 patients." (PMID 34667241, 2021). "Finally, IL-6, MAPK3, MAPK1, MAPK14, MAPK8, IL-1β, CCL2, EGFR, PPARG, and NOS2 were declared key targets of XFBD for COVID-19." (PMID 35185537, 2021). "The only expression of IL-1α, IL-1β, IL1 receptor and their signaling pathway molecules had been induced before the lowest respiratory system function (up to 3-5 days after the onset of COVID-19 symptoms) in patients with poor outcomes." (PMID 35126355, 2021). "However, additional investigation into the lung-specific cellular source of the proinflammatory cytokines typical of severe COVID-19, including IL-6, tumor necrosis factor–α (TNF-α), IL-1β, and IL-17A, is needed." (PMID 33622974, 2021). "We found that statins may be effective by ameliorating endothelial dysfunction triggered by cytokine storm cytokines/chemokines (IL-6, TNF-α, IL-1β, CCL2, interferons, and related factors) released from COVID-19 patients." (PMID 34253708, 2021). "Moreover, COVID-19 can bind the Toll-like receptor (TLR) to induce the release of pro-IL-1β, which is cleaved into the active mature IL-1β mediating lung inflammation, until fibrosis." (PMID 33995053, 2021). "IL1B mRNA levels were not different in the upper and lower airways of hospitalized COVID-19 patients, while IL6 transcripts appeared to be predominantly expressed in the nasopharyngeal swabs compared to the BALF." (PMID 34492226, 2021). "Some type 2 cytokines (IL-4, IL-9, IL-13, etc.)have inhibitory effects on the production of proinflammatory cytokines (IL-1β, IL-6, TNF-α, etc.), the overactivation of which have been proposed as a potential key mechanism of protection against COVID-19 to some extent." (PMID 35082829, 2021). "It was then determined that despite systemic and placental increases in inflammation markers, such as IL-1β and IL-6, little to no symptoms of COVID-19 presented." (PMID 34564316, 2021). "Cytokines IL-18 and IL-33 were higher and IL-1β was lower in COVID-19 non-ICU patients versus controls (FDR < 0.1 or < 0.05)." (PMID 34960684, 2021).
COVID-19 (continued). "The cytokines interleukin 6 (IL-6), interleukin 1 beta (IL-1β), tumor necrosis factor alpha (TNF-α) and chemokine C–C motif ligand 2 (CCL2), 3 (CCL3), and 5 (CCL5) are upregulated and represent potential targets for treatment of patients with COVID-19." (PMID 33521616, 2021). "However, studies showed that these patients with COVID-19 present a high expression of tumor necrosis factor (TNF)-α, interleukin (IL)-1β, and IL-6." (PMID 33776796, 2021). "Moreover, high levels of IL-1β and IL-6 have been identified in SARS-CoV-2-infected subjects, and single-cell transcriptomic analysis of peripheral blood in COVID-19 patients also show increased subsets of IL-1β-producing monocytes." (PMID 33790857, 2021). "Since IL-1β is in part responsible for the cytokine storm by SARS-CoV-1 and MERS-CoV38,39, ORF7a may play a significant role in the clinical severity of COVID-19." (PMID 34188167, 2021). "In addition, it has become clear that abrupt release of IL-1β and TNF-α also contributes significantly to the severity of COVID-19 pathogenesis." (PMID 33959020, 2021). "A reduction in serum levels of IL-6, IL-1β, and TNF-α, rapid recovery of circulating T and B cell frequencies, and increased antibody production against the SARS-CoV-2 spike protein has been reported in severe COVID-19 cases treated with this agent." (PMID 34590796, 2021). "High plasma levels of tumor necrosis factor-α (TNF-α), IL-1β, IL-6, and IL-8 have been confirmed in COVID-19, especially in non-survivors and in critically ill patients." (PMID 34177896, 2021). "Some patients with severe COVID-19 experience cytokine release syndrome (CRS) or a cytokine storm—elevated levels of hyperactivated immune cells—and circulating pro-inflammatory cytokines, including interleukin (IL)-1β and IL-18." (PMID 34360684, 2021). "Whereas serum of non-COVID-19 patients and anti-spike IgG-negative COVID-19 patients showed no up-regulation of pro-inflammatory cytokines compared to individual poly(I:C) stimulation, IL-1β, IL-6, IL-8, and TNF production was amplified by serum of COVID-19 patients with anti-spike IgG (P <0.0001)." (PMID 33979301, 2021). "Therefore, this network also displays the contribution of increased pro-inflammatory molecules or signaling pathways (IL1B, IL6, IL8, IL17a) and upregulated chemokine signaling (CXCR4 signaling, CCL5) observed in severe COVID-19 outcomes." (PMID 33941085, 2021). "As shown by a study on 452 patients, markedly elevated levels of IL-6 and slightly enhanced levels of TNF and IL-2R, while no marked change of IL-1β, were observed in COVID-19 patients." (PMID 33907514, 2021). "Furthermore, patients with COVID-19 exhibited hyper-inflammatory signatures across all types of cells among PBMCs, particularly upregulation of the TNF/IL-1β-driven inflammatory response and type I IFN responses." (PMID 33674719, 2021). "Subsequently, to further determine whether SARS-CoV-2 infection in AAV/hACE2 mice model could also induce proinflammatory mediators as shown in severe COVID-19 patients, RNA levels of TNF-α, IL-1β, IL-6, CCL2, and CXCL10 in mice lung homogenates were measured." (PMID 34379705, 2021). "Serum IL-1β and TNF-α levels are obviously elevated in patients with severe COVID-19." (PMID 33404925, 2021). "In addition, COVID-19 patients with severe disease have been shown to suffer from a rapid and excessive production of harmful pro-inflammatory cytokines (IL6, IL1-β, and TNF-α), or “cytokine storm”, triggered by the innate immune response against the virus." (PMID 34031383, 2021). "Consistent with systemic inflammation, COVID-19-derived PBMCs but not HC cells spontaneously released IL-1β, and also IL-6 and TNF-α ex vivo (respectively)." (PMID 35095880, 2021). "Indeed, among the deceased patient of COVID-19, the level of TNF-α, IL-6, IL-1β, and IL-8, were the highest when compared to recovered cases." (PMID 33632295, 2021).